MMP9 (matrix metallopeptidase 9)
Diseases named in the same sentence as MMP9 in open-access papers (continued):
Sharing a sentence is not in itself a finding about the gene and the disease.
cholesteatoma (continued). "There are some uncertainties about whether MMP-9 is upregulated in cholesteatoma compared to unchanged skin." (PMID 35655767, 2022). "stated that it is related to MMP-9 overexpression in cholesteatoma in comparison to unchanged skin." (PMID 35655767, 2022). "It suggests that TIMP-4 is interconnected to MMP-9 in cholesteatoma." (PMID 35655767, 2022). "Also, TIMP-1, which is an MMP-9 specific inhibitor, was found to be upregulated in cholesteatoma, and it indicates that there is a dynamic balance between these two remodeling factors in cholesteatoma." (PMID 35655767, 2022). "Yet, it is still unclear how exactly TIMP-2 affects MMP-2 or MMP-9 in cholesteatoma tissue." (PMID 34682191, 2021). "The elevated c-MYC expression we have detected previously in cholesteatoma might contribute to the increased MMP9 expression since the MMP9 promoter harbors a c-MYC binding site." (PMID 30021014, 2018). "In case of MMP9 mRNA expression was significantly elevated in recurrent cholesteatoma samples compared to the normal skin (μ±SD = 1.351 × 10−1 ± 0.276 for recurrent cases and μ±SD = 1.046 × 10−1 ± 0.2336 for control samples; the K-W test followed by Dunn’s P< 0.05)." (PMID 30021014, 2018). "Therefore, the MMP expression levels were tested using Real-time PCR, and the results revealed that the expression levels of MMP-2 (p < 0.01), MMP-8 (p < 0.001) and MMP-9 (p < 0.01) were significantly increased in human acquired cholesteatoma (n = 10) compared with the normal skin (n = 10)." (PMID 27934908, 2016). "The main goal of our study was to describe the transcription factor (NF-κβ), angiogenetic factor (VEGF), and remodeling markers (MMP-9 and TIMP-4) of the cholesteatoma tissue compared to control skin tissue." (PMID 35655767, 2022). "Correlation between MMP-9 and TIMP-4 suggests that TIMP-4 in cholesteatoma tissue intercorrelates to MMP-9." (PMID 35655767, 2022). "Two of the enzymes proven to play an important role in the pathogenesis of cholesteatoma are Matrix metalloproteinase-2 (MMP-2) and Matrix metalloproteinase-9 (MMP-9)." (PMID 34682191, 2021). "In human acquired cholesteatoma, the expression of proinflammatory cytokines (IL-1β, TNF-α and IL-6) and matrix metalloproteinases (MMP-2, MMP-8 and MMP-9) were up-regulated, and their expression levels were positively correlated with TREM-2 expression." (PMID 27934908, 2016). "Among the 811 up-regulated extramatrix protein genes, MMP1, MMP7, MMp9, MMP10 and MMP12 and their substrate Osteopontin (SPP1) were amplified and their expression was significantly higher in cholesteatoma than in external canal skin (logFC>10)." (PMID 23285167, 2012). "Specific cholesteatoma MMP isoenzymes (MMP2, MMP3, and MMP9) were first identified in 199617 with the use of immunohistochemistry tests." (PMID 22714856, 2012). "The distribution and appearance of the MMP-9-positive cells ranged from none to moderate (++) in the cholesteatoma and from occasional (0/+) to few-to-moderate (+/++) in the skin epithelium." (PMID 36837507, 2023). "Therefore, the aim of our work was to describe the distribution of transcription factor (NF-κβ), angiogenetic factor (VEGF), and remodeling markers (MMP-9 and TIMP-4) of the cholesteatoma." (PMID 35655767, 2022). "As we proved intercorrelation between MMP-9 and TIMP-4 in cholesteatoma, we suggest that these remodeling factors might also influence bone remodulation in middle ear bone." (PMID 35655767, 2022). "Additionally, we found that TIMP-4 in the cholesteatoma matrix has a very strong positive correlation with MMP-9 and a moderate correlation between TIMP-4 in matrix and MMP-9 in perimatrix." (PMID 35655767, 2022). "In cholesteatoma matrix metalloproteinases MMP1, MMP9, MMP10, and MMP12 were up-regulated." (PMID 23285167, 2012). "In addition to already described up-regulated mRNAs in cholesteatoma, such as MMP9, DEFB2 and KRT19, we identified 3558 new cholesteatoma-related transcripts." (PMID 23285167, 2012).
cholesteatoma (continued). "In addition, our study revealed that many samples of cholesteatoma were also negative or weakly stained for MMP-9 immunohistochemically." (PMID 38535082, 2024). "Real-time PCR of PI3, SPRR1B, LCN2 (lipocalin 2), MMP1, MMP9, MMP10, MMP12, SPP1, GJB2, Bcl-xl (BCL2L1), cIAP2 (BIRC3), S100A7A (koebnerisin), S100A9, SERPINB3, CEACAM6, KRT6B and SERPINB4 revealed that the expression levels of these proteins were higher in cholesteatoma than in external canal skin." (PMID 23285167, 2012).
chronic heart failure (16 papers, 2011 to 2025). "The MMP‐9 levels and associated inflammatory cytokines were previously related to acute cardiovascular events, disease severity in chronic heart failure and adverse outcomes in these patients." (PMID 31932967, 2021). "Further, MMP9 not only plays an important role in the acute phase of MI, but also exacerbates the progression of chronic heart failure by inhibiting autophagic flux." (PMID 40630623, 2025). "Elevated MMP-9 levels correlate with adverse left ventricular (LV) remodeling, reduced ejection fraction, and persistent inflammation in chronic heart failure." (PMID 41009942, 2025). "Recent studies have shown that MMP9, an enzyme that extensively degrades ECM, regulates cardiomyocyte autophagy, and inhibiting MMP9 increases autophagic flux, thereby preventing congestive heart failure after MI." (PMID 37759781, 2023). "Additionally, it was shown that chronic heart failure involves endothelial apoptosis in response to MMP-9 activation." (PMID 25888309, 2015). "In the development of chronic heart failure, the activation of matrix metalloproteinase-2 (MMP-2) and matrix metalloproteinase-9 (MMP-9) plays a significant role, particularly in the early and late stages." (PMID 39201469, 2024). "Deletion of MMP-9 stimulates neovascularization, and MMP-9 inhibits apoptosis of endothelial cells in a chronic heart failure model." (PMID 33805901, 2021). "However, plasma MMP9 has also been reported to serve as a useful prognostic tool in patients with AMI, where during the 2-year follow-up plasma MMP9 levels (but not MMP2, TNFα, C-reactive protein, creatine kinase or pro-BNP) were the only predictive of late-onset congestive heart failure." (PMID 22943504, 2012).
experimental autoimmune encephalomyelitis (16 papers, 2009 to 2025). An autoimmune demyelinating disease of the central nervous system that is produced experimentally in animals by the injection of homogenized brain or spinal cord in Freund's adjuvant. "After treatment with CD147-blocking antibodies, the improved outcome in the experimental autoimmune encephalomyelitis mice was associated with diminished MMP9 proteolytic activity." (PMID 31926558, 2020). "CD147 is an upstream mediator of MMP-9 activity and has been linked to an increased inflammatory response and enhanced leukocyte recruitment in models of experimental autoimmune encephalomyelitis, where inhibition of CD147 blocks leukocyte entry and reduces disease severity." (PMID 32191628, 2020). "MMP-9 is furthermore involved in the pathophysiological process underlying many inflammatory diseases: It was already shown in 1999 that genetically MMP-9-deficient mice develop more severe experimental autoimmune encephalomyelitis (EAE) than wildtype littermates." (PMID 23139770, 2012). "The underlying molecular mechanisms are diverse due to the broad substrate specificity of MMP-9, as demonstrated by secretome analysis in murine experimental autoimmune encephalomyelitis, which uncovered 119 potential MMP-9 substrates." (PMID 38424488, 2024). "Further analysis showed that CD147 colocalized with MMP9 protein and displayed activity in experimental autoimmune encephalomyelitis brain tissues." (PMID 31926558, 2020). "Leukocyte-derived MMP9 is also required in EAE (Experimental autoimmune encephalomyelitis) for initial infiltration into the blood-brain barrier." (PMID 31440381, 2019). "Moreover, increased PRDX6 expression in experimental autoimmune encephalomyelitis (EAE) mice led to reduced myelin loss, decreased MMP9 levels, and dampened microglial activation, thereby preserving BBB integrity and limiting immune cell infiltration." (PMID 40918143, 2025). "Therefore, similarly to what was observed in experimental autoimmune encephalomyelitis, our data suggest that loss of MMP-2 activity in hepatic IRI exacerbated disease, in part, by augmenting MMP-9 secretion." (PMID 26355684, 2015). "An increase of MMP-9 expression in the absence of MMP-2 activity was previously observed in experimental autoimmune encephalomyelitis." (PMID 26355684, 2015).
gastric adenocarcinoma (16 papers, 2011 to 2025). "MMP9 overexpression is frequently found in gastric adenocarcinoma cells and is associated with the aggressive phenotype and poor prognosis." (PMID 35773363, 2022). "In gastric adenocarcinoma, MMP9 may be implicated in tumor progression and has potential use as a diagnostic and prognostic biomarker." (PMID 35773363, 2022). "The aim of this study was to investigate whether the expression of MMP2, MMP7, and MMP9 in humans is associated with the expression of mTOR in its “naïve” and its phosphorylated (active) form in different topographical regions of gastric adenocarcinomas." (PMID 26652716, 2015). "Specifically, the inhibitory effects of RA on the activity of matrix metalloproteinase 9 (MMP-9), which plays a vital role in cancer progression and the formation of metastases in gastric adenocarcinoma CRL-1739 cells, were reported." (PMID 40565721, 2025). "In conclusion, our results demonstrate that LPE appears to be a protective agent against the insurgence of human gastric adenocarcinoma since it can reduce the upregulation of key enzymes such as MMP-9 and MMP-2 that occur during the inflammation process." (PMID 31817563, 2019). "Furthermore, melatonin has reduced the expression of MMP–9 in a human gastric adenocarcinoma cell line and another mechanism of MMP–inhibition through a direct interaction of melatonin with Pro421 and Ala191 at the catalytic centre of MMP–9 has been found." (PMID 36299487, 2022). "Astragalus saponins have also been found to inhibit human gastric adenocarcinoma cell proliferation and invasion by downregulation of the proangiogenic protein VEGF as well as the metastatic proteins metalloproteinase-2 (MMP-2) and MMP-9." (PMID 24963322, 2014). "The human gastric adenocarcinoma cell line AGS responded to IL-21 by increasing the production of MMP-2 and MMP-9 in a NF-kB-dependent fashion and treatment of H. pylori-infected gastric explants with an antibody against IL-21 decreased the production of epithelial cell-derived MMP-2 and MMP-9." (PMID 36769214, 2023). "Although serum CK18, MMP-9, and TIMP1 preop measurements in patients scheduled for curative surgery due to gastric adenocarcinoma did not help to gain any idea of tumor resectability, we concluded that our study had valuable results in significantly predicting N3 stage." (PMID 29651326, 2018).
gastritis (16 papers, 2016 to 2025). Inflammation of the stomach. "Treatment with antibiotics and the proton pump inhibitors led to decreased levels of total and active MMP-9 in the gastric mucosa of both the antrum and the corpus parts in H. pylori–associated gastritis patients." (PMID 35163805, 2022). "Furthermore, adults with H. pylori-associated gastritis had increased levels of MMP-9 and decreased levels of MMP-2 and TIMP-1 in serum in comparison to healthy volunteers." (PMID 37958643, 2023). "Our study also assessed mRNA for MMPs and TIMPs and the results revealed a higher expression of mRNA for MMP-9 along with a low expression of mRNA for MMP-2 in the gastric mucosa of children with H. pylori-related gastritis." (PMID 37958643, 2023). "In the IL-8-251 AA genotype Koreans, there was a significant correlation between the MMP-9 level and progression from H. pylori infection to chronic atrophic gastritis/intestinal metaplasia and gastric adenocarcinoma." (PMID 35163805, 2022). "Incubated for 24 h in cell culture medium, gastric mucosal biopsies from H. pylori–positive patients with chronic superficial gastritis produced higher levels of MMP-9 and TIMP-1, in comparison with biopsies from H. pylori–negative individuals." (PMID 35163805, 2022). "Several studies demonstrated a correlation between the elevated serum levels of MMP9 and higher MMP9 activity in antral mucosa of H. pylori-infected patients with gastritis." (PMID 34492072, 2021). "The objective of this study was to investigate the serum levels of IL-10, MMP-7 & MMP-9 in gastritis patients with H. pylori infection." (PMID 27703556, 2016). "Moreover, the transcriptional level of MMP-9 was completely alleviated by lgfAv treatment in alcohol-treated gastritis-induced mice." (PMID 28874080, 2017). "The results indicated that in H. pylori-positive patients with gastritis, the serum levels of myeloperoxidase, neutrophil elastase, MMP-8, and MMP-9 increased significantly." (PMID 37605137, 2023). "Of which, MMP9, CXCL2, CXCL8, and IL-10 were part of the 15 common genes, and these four genes are significantly upregulated between gastritis patients and normal control." (PMID 34471638, 2021). "We demonstrated that the culture supernatant of CD4+T cell from H. pylori-positive gastritis patients promoted MMP3 and MMP9 secretion of GES-1 cells." (PMID 34589088, 2021). "In addition, PTGS2, TRL4, MMP9, JAK1, EGFR, CYP2C19, and PTGS1 were identified as crucial anti-gastritis target genes in C. cassia." (PMID 35336597, 2022). "PTGS2, NOS2, EGFR, MMP9, CXCL2, CXCL8, and IL-10 may be the important direct targets of Weibing Formula 1 in gastritis treatment." (PMID 34471638, 2021). "In addition to IL-10, MMP9, CXCL2, and CXCL8 expression levels were significantly increased in gastritis patients compared with the control group, which was consistent with the GSE60427 and GSE5081 results." (PMID 34471638, 2021). "Our results also suggested that the reduced gastritis in AM1/SS1 infected mice may be is due to reduced activation of Th17/IL-17 pathway and subsequent downregulation of MMP9 and 3 expressions in AM1/SS1 infected group." (PMID 28286572, 2017). "In this study, the objective is to evaluate the increase of IL-10, MMP-7 and MMP-9 in patients with H. pylori infection without any systemic disease and the correlation with the histopathologic degree of gastritis." (PMID 27703556, 2016). "Furthermore, gastric mucosa biopsies from H. pylori-positive patients with gastritis after incubation with culture medium also produced higher levels of MMP-9 and TIMP-1 than biopsies from H. pylori-negative patients." (PMID 37958643, 2023). "The increased synthesis of MMP-9 can stimulate ulcerogenic properties of this MMP in the gastric mucosa so the evaluation of this MMP in plasma, as well as in circulating lymphocytes, can be used as an easy refractory H. pylori-induced gastritis or peptic ulcer marker in children." (PMID 37958643, 2023).
gastritis (continued). "In conclusion, the potential mechanism of Weibing Formula 1 in treating gastritis has the multicomponent, multitarget, and multiway characteristics, and PTGS2, NOS2, EGFR, MMP9, CXCL2, CXCL8, and IL-10 may be the important direct targets of Weibing Formula 1 in gastritis treatment." (PMID 34471638, 2021). "Although a direct interaction between MMP-9 and chymase in gastritis has not been reported, the role of MMP-9 activation by chymase in the development of gastritis should be studied in the future." (PMID 36289761, 2022).
rectal cancer (16 papers, 2000 to 2022). A primary or metastatic malignant neoplasm that affects the rectum. "Remarkably, treatment with GOFA in LPS stimulated cell lines significantly abrogated MMP-9 activity with a similar entity caused by ROS scavenger pretreatment, highlighting a greater significance on the monocytic cells compared to the colon rectal cancer cell." (PMID 32492880, 2020). "Low levels of MMP-9 indicated poor prognosis among rectal cancer patients (HR 0.49, 95% CI 0.28–0.85, P = 0.011)." (PMID 29929486, 2018). "Increased type-IV collagenase activity (MMP-2 and MMP-9) following preoperative RTX in rectal cancer was recently discovered." (PMID 19323831, 2009). "In present study, we also revealed a significant elevated expression of NGAL and MMP-9 mRNA levels in human rectal cancer and they all correlated well with tumor invasion and metastasis." (PMID 19419554, 2009). "The mRNA expression of NGAL and MMP-9 was examined in 100 rectal cancers and paired normal rectal tissues." (PMID 19419554, 2009). "In present study, we detected the mRNA expression of NGAL and MMP-9 in human rectal cancer by real-time RT-PCR." (PMID 19419554, 2009). "This is the first study to apply the real-time RT-PCR method to quantify the NGAL mRNA expression and to elucidate the correlation of NGAL mRNA expression with clinicopathologic features and MMP-9 in human rectal cancer." (PMID 19419554, 2009). "NGAL mRNA up-regulation was correlated significantly with tumor progression and MMP-9 mRNA overexpression in rectal cancer, suggesting a more aggressive phenotype." (PMID 19419554, 2009). "We designed this study to determine any differences in the expression of MMP-2, MMP-9 and uPA system between colon and rectal cancer tissues." (PMID 16916471, 2006). "In rectal cancer, high MMP-9 and high TIMP-1 served as prognostic factors." (PMID 29929486, 2018). "Therapeutic agents that inhibit the expression or function of NGAL or of its target genes may prove efficacious, or might complement agents that directly compromise the MMP-9 activities in the treatment of human rectal cancer." (PMID 19419554, 2009). "We found that MMP9, MYC, and VEGFA were upregulated in the rectal cancer group compared with normal tissue." (PMID 28689994, 2017). "Among the 100 rectal cancer RNA samples tested, NGAL and MMP-9 over expression were shown in 69 and 63 cases respectively." (PMID 19419554, 2009). "In rectal cancers, the correlation coefficient between mRNA up-regulation of NGAL and MMP-9 was 0.393." (PMID 19419554, 2009). "Rectal cancer specimens expressed both pro (72 kDa) and active (62 kDa) forms of MMP-2 but only the pro form of MMP-9 (92 kDa)." (PMID 10732772, 2000). "Its association with clinicopathologic characteristics and expression of MMP-9, one of its target genes, has not been reported systematically in rectal cancer." (PMID 19419554, 2009). "Its association with clinicopathologic characteristics and expression of MMP-9, one of its target genes, in rectal cancer has not been reported systematically." (PMID 19419554, 2009). "Moreover, preoperative radiotherapy leads to a significant increase in the levels of MMP-2 and MMP-9 in rectal cancer tissues without their correspondent increase in normal mucosa." (PMID 30336548, 2018). "Therefore, to further determine the potential involvement of NGAL in rectal cancer, we have evaluated the expression level of NGAL mRNA by real time RT-PCR, and further elucidated the correlation of NGAL mRNA expression with clinicopathologic features and MMP-9 in rectal cancer." (PMID 19419554, 2009).